TWIST1 (twist family bHLH transcription factor 1)
Diseases named in the same sentence as TWIST1 in open-access papers (continued):
Sharing a sentence is not in itself a finding about the gene and the disease.
tumor (continued). "Our study showed that PDGF-D was highly expressed in CRC tissues and it could promote tumor growth, invasion, angiogenesis, and EMT transformation by activating Notch1/Twist1 axis." (PMID 28035069, 2017). "Our results support that the Bcl-2/Twist1 complex induces EMT and facilitates tumor metastasis in OSCC, which might represent a powerful strategy for developing of novel OSCC therapies." (PMID 28032603, 2017). "To mimic the primary tumour, where only a small percentage of cells may express EMT-TFs4, we co-cultured GFP+HMLER-Control (HMLER-Ctrl) cells with tRFP+HMLER-Snail1 or Twist1 cells in a 1:1 or 10:1 ratio and performed migration assays." (PMID 28604738, 2017). "Moreover, in the same Group 1, where TWIST1 was overexpressed in the tumor site, we noted also a positive correlation between nuclear NHERF1 and TWIST1." (PMID 29152120, 2017). "Importantly, the authors show that Twist1 silencing at distant sites allowed the reversion of EMT to MET, which was a requisite for disseminated tumor cells to grow and form detectable metastases." (PMID 28590039, 2017). "(2015) reported that genetic suppression of Snail1 or Twist1 in primary pancreatic ductal adenocarcinomas (PDACs) did not alter tumor progression or metastatic outgrowth, thus concluding that EMT was dispensable for metastasis." (PMID 28590039, 2017). "TGF-β can also induce fibulin 5 (FBLN5), which promotes tumor invasion and epithelial-mesenchymal transition (EMT) by elevating Twist1 transcription and reducing E-cadherin expression, although the precise mechanism by which FBLN5 regulates Twist1 transcription remains elusive." (PMID 28099910, 2017). "One likely explanation for the lack of effects on metastasis upon deletion of SNAIL1 or TWIST1 is due to redundant functions of multiple EMT‐TFs in inducing EMT in this KPC tumor model." (PMID 28085222, 2017). "In CRC, the expression of TWIST1 and TWIST2 is generally restricted to the tumor stroma." (PMID 29258163, 2017). "Interestingly, recent studies have demonstrated that phospho-Twist1 mediates cross-talk between PI3K/Akt and TGF-β1 signaling and promotes tumor metastasis." (PMID 27533085, 2016). "The appearance of TWIST1 in our 8-gene CTC predictor is remarkable since our applied CTC isolation method relies on an EpCAM-based enrichment step and tumor cells undergoing EMT might become EpCAM-negative." (PMID 26892682, 2016). "A number of groups have recently reported an essential role for Twist1 in tumor initiation that would be independent of its EMT-inducing activity, but related to its effects on inhibiting apoptosis." (PMID 26985909, 2016). "Subsequently, IHC analysis of the obtained tumor sections confirmed the diminished stromal staining of MARCKS activation and AKT signaling, as well as the attenuated stromal Twist1 expression and the resultant αSMA staining, in the sh-MARCKS group compared with that of the sh-NC co-injection group." (PMID 27081703, 2016). "Members of the EMT regulating transcription factor families such as SNAI1/2, TWIST1/2 and ZEB1/2, are well-known as key inducers of invasion and metastasis in epithelial cancers through the conversion of tumour cells from an epithelial to a mesenchymal-like state." (PMID 27470974, 2016). "Given its well-characterized function in promoting metastasis, we will also investigate the role of TWIST1 in the spread of EOC cells throughout the peritoneal space, from primary tumours of the ovary, the fallopian tube epithelium, and pockets of CSCs during recurrence." (PMID 27876874, 2016). "Prominent stromal cell staining for TWIST1 and TWIST2 could be noted with only very infrequent expression within tumor epithelia." (PMID 25528769, 2015). "We observed lack of correlation between hypermethylation and protein expression in normal colorectal mucosa may suggest that hypermethylation as a regulatory mechanism of TWIST1 and TWIST2 may be restricted to the tumor microenvironment." (PMID 25528769, 2015).
tumor (continued). "Eleven cancer related genes were found to have methylation (defined as more than 10 % methylation) in at least some of the tumours: RASSF1A (64 %), TWIST1 (61 %), CDH13 (51 %), APC (50 %), MAL (35 %), GSTP1 (30 %), WIF1 (26 %), RARβ (19 %), BRCA1 (2 %), CDKN2A (2 %) and TP73 (2 %)." (PMID 26452468, 2015). "Presumably, the most favorable (possibly default) state for the tumor is one in which TWIST1 and TWIST2 are not prevented from being expressed, thus allowing these genes to exert their functions and facilitating and progression." (PMID 25528769, 2015). "Thus, clarifying the regulatory mechanism of TWIST1 expression would provide insight into the regulatory pathway of TWIST1-induced EMT programming and aid in developing molecular targets to inhibit tumor metastasis." (PMID 25848863, 2015). "Moreover, nuclear expression of MACC1, TWIST1, and TWIST2 was upregulated in GC tissues compared with matched adjacent non-tumorous tissues (p < 0.05)." (PMID 25895023, 2015). "In addition, A20 functions as a tumor suppressor in the progression and metastasis of HCC through a mechanism involving inhibition of Twist1 expression via suppressing NF-κB activation." (PMID 26538215, 2015). "TWIST1 and TWIST2 CpG methylation was correlated to protein expression and tumor budding status." (PMID 25528769, 2015). "In addition, we found that the nuclear expression of MACC1, TWIST1, and TWIST2 proteins was significantly higher in the tumor tissues of VM-positive GC patients than in their matched adjacent non-tumor tissues (p = 0.045, p = 0.015, and p = 0.007)." (PMID 25895023, 2015). "The mechanism by which this segregation happens is still unclear and further investigation is needed, but perhaps, co-expression of TWIST1 and ZEB2 could identify patients with undetected tumor spread." (PMID 26214683, 2015). "In accordance with our results of a possible inverse relationship between methylation and tumor budding phenotype, we observe a significant hypermethylation of TWIST1 and TWIST2 in correlation with low-grade budding and a hypomethylation of TWIST1 and TWIST2 in the high-grade budding tumor." (PMID 25528769, 2015). "In this study, we demonstrate, for the first time, that in wild-type N-cadherin cancer models, metformin plays an anti-tumor role through repressing TWIST1/N-cadherin/NF-kappaB signaling, independent of activation of AMPK." (PMID 26359363, 2015). "In order to determine whether the hypermethylation of TWIST1 and TWIST2 as a mechanism for TWIST1 and TWIST2 down-regulation is restricted to tumor, we included analysis of 10 normal colonic tissues." (PMID 25528769, 2015). "Our results suggest that the pro-tumor effects of TWIST1 and, to some degree, TWIST2 come from the tumor stroma and that this expression may be regulated at least in part by promoter hypermethylation." (PMID 25528769, 2015). "TWIST1 and PDCD4 expression was associated with the degree of tumor differentiation but not sex or age (p = 0.021 and p = 0.013)." (PMID 25144746, 2014). "EMT-related transcription factors such as TWIST-1, snail, slug, ZEB1, and ZEB2 orchestrate the EMT, and enable the early steps of metastasis, which consist primarily of local invasion and the subsequent dissemination of tumor cells to distant sites." (PMID 25326651, 2014). "The early overexpression of TWIST1 may be attributed to its regulation by the NKX3-1 gene, a tumor suppressor that was found to be underexpressed in the early stages of PCa." (PMID 25409297, 2014). "Further investigation confirmed that PI3K/AKT/HIF-1α signaling activated by Gankyrin could promote Twist1, VEGF, and metalloproteinase 2 expression, and also promote EMT and motility/invasion of tumor cells." (PMID 24751719, 2014).
tumor (continued). "We have not observed any statistically significant correlation between expression of VIM, TWIST1 or SNAI1 (analyzed together or separately) in CTCs-EBF and histological type of the tumor (ductal vs. lobular, p = 0.48) or molecular subtype of the primary tumor (p = 0.93, data not shown)." (PMID 24217115, 2013). "Thus, Twist1 represents a single factor that can intimately link two cellular processes, EMT and maintenance of a stem cell-like fate, both integral to tumor cell progression." (PMID 23555309, 2013). "Additionally, some other loci showing significant differences in DNA methylation levels between tumor and non-tumor lung tissue have been identified, including: CDKN2A EX2, CDX2, HOXA1, SFPR1, and TWIST1 gene." (PMID 23086271, 2013). "Apparently, TWIST1 protein is predominantly localized in the nuclei of both epithelial tumor cells and in almost all non-epithelial cells present in the stromal compartment of tissues, such as fibroblast cells, endothelial cells and inflammatory cells." (PMID 22967435, 2012). "Ectopic PRDM5 expression significantly inhibited tumor cell clonogenicity, accompanied by the inhibition of TCF/β-catenin-dependent transcription and downregulation of CDK4, TWIST1 and MDM2 oncogenes, while knocking down of PRDM5 expression lead to increased cell proliferation." (PMID 22087297, 2011). "Another study correlated high tumor grade to Twist1 expression in HNSCC cases and while not statistically significant, Twist1 expression was associated with poor prognosis." (PMID 24212639, 2011). "The oncogenic role of Twist1 is not in facilitating cell transformation but rather it facilitates the ability of the cells within a primary tumor to undergo a pathological EMT similar to its function in development." (PMID 18855684, 2008). "EMX2 exerts tumor-suppressive functions in TNBC by directly binding to the E-cadherin promoter to maintain the epithelial phenotype and by repressing the expression of key EMT transcription factors such as TWIST1, thereby inhibiting EMT and cancer stem cell (CSC) properties." (PMID 40969325, 2025). "Importantly, lymph node metastases were enriched in EMT-related gene programs and transcriptional circuits such as those driven by ZEB1, TWIST1, and TGIF2, which are known to fuel the mesenchymal shift in tumor cell states facilitating dissemination and survival in secondary sites." (PMID 41279557, 2025). "Because EMT initiation is a critical process in tumour progression, we evaluated the effect of BEST4 on EMT using quantitative polymerase chain reaction (qPCR) and found that BEST4 expression upregulated CDH1 and TJP1 and downregulated VIM and TWIST1 in HCT116 compared with the control (p<0.05)." (PMID 39699952, 2024). "They reported that the TWIST1 promoter exhibited excellent sensitivity and specificity in detecting BUC in urine samples, suggesting that aberrant DNA methylation could serve as a potential molecular tumor biomarker for BUC detection." (PMID 38575639, 2024). "Furthermore, we established an in vivo liver orthotopic transplantation model, which showed that Twist1 overexpression promotes tumor growth in mice, and VDBP supplementation significantly inhibited the Twist1-induced effects and prolonged the survival of mice." (PMID 38164156, 2024). "To further explore the role of TWIST1 in MET driven NSCLC in vivo, we silenced TWIST1 in the MET exon 14 skipping mutant NSCLC cell line H596 and found that genetic inhibition of TWIST1 led to a significant decrease in tumor growth (68% reduction in mean tumor size)." (PMID 38485737, 2024). "Notably, combination treatment with Twist1 siRNA LNP and Egfrviii CAR T cells substantially extended animal survival (+8.5 days, P < 0.0001) and delayed tumor growth (left), showing comparable therapeutic efficacy to combination therapy with harmine and CAR T cells." (PMID 38416830, 2024).
tumor (continued). "Furthermore, Twist1 deletion in ECs did not affect tumor angiogenesis or basal development, as indicated by apparently normal mouse development with unaltered vascular density manifested by numbers of CD31+ ECs in the tumors." (PMID 38416830, 2024). "Additionally, NF-κB promotes tumor metastasis by inducing epithelial–mesenchymal transition (EMT) through the activation of transcription factors, such as Twist1 and Snail, and by regulating selectins and integrins involved in cancer cell migration and colonization at distant sites." (PMID 39518013, 2024). "Upon depletion of USP51, TWIST1 is polyubiquitinated and subsequently degraded by the proteasome, resulting in a decrease in NSCLC cell stemness and in vivo inhibition of tumor growth; these finding suggest that USP51 could be a candidate therapeutic target for NSCLC." (PMID 37422632, 2023). "Thus, to further understand tumor invasiveness specifically induced by JICD1/SMAD3-TWIST1 axis, we compared tumors derived from control, JICD1-overexpressing, and JICD1-overexpressing with TWIST1 knockdown U87MG cells." (PMID 38092725, 2023). "The tumor immune microenvironment can also affect EMT programs, since FN1 and CRB3 marker genes are IFN-regulated ones (IRG = IFN-regulated gene); furthermore, some of the TFs of EMT are all regulated by IFN: SNAI1, TWIST1/2, ZEB1/2, SIX1, SOX4, and TCF4, according to the Interferome database." (PMID 36754910, 2023). "Also noteworthy, EMT-TFs may have opposing roles in a particular tumor type, such as melanoma, where ZEB1 promotes EMT programs with the help of TWIST1, while ZEB2 in cooperation with SNAI2/SLUG are inhibitors." (PMID 36754910, 2023). "SNAI2, TWIST1, and ZEB1 are the key regulatory genes contributing to the EMT process, where SNAI2 silencing substantially inhibits the EMT process, and overexpression of constitutively active TWIST1 in tumour cells promotes the acquisition of conspicuous EMT characteristics." (PMID 37686338, 2023). "Indeed, aberrant expression of EMT‐TFs, such as Twist1, SIP‐1, and Snail, in cancer cells contributes to the acquisition of stem‐cell features, as evidenced by the increased self‐renewal ability in vitro and tumor propagation potential in vivo." (PMID 35601657, 2022). "The ectopic expression of TWIST1 in head and neck squamous cell carcinoma cells triggers EMT and leads to the acquisition of mesenchymal phenotypes of tumor cells, while the increased proportion of CD44-labeled cells in the tumor population can activate tumor initiation." (PMID 35637953, 2022). "Finally, by multivariate analysis, high PD-L1 and TWIST1 expression was found to be independent and negative prognostic factors for tumor recurrence in NMIBC patients." (PMID 34885101, 2021). "Another hypothesis is that EMT-TFs expression is organ (and therefore) tumor specific, e.g., Snai1 and Twist1 are not necessary in mouse model of pancreatic cancer, while Zeb1 knock-out reduces metastasis of about 30%." (PMID 34768901, 2021). "Rescue experiments indicated that Twist1 may mediate the tumor-suppressive effect of miR-361-5p in HCC cells, and this was supported by the effect of miR-361-5p on inhibiting the epithelial-mesenchymal transition (EMT) by targeting Twist1." (PMID 33381597, 2020). "To further assess the relevance of JPX and Twist1, we divided the lung cancerous specimens into two groups: the “JPX high” and “JPX low” groups, which had higher or lower JPX expression, respectively, in tumor tissues than that in the paired adjacent non-tumor tissues." (PMID 31941509, 2020). "Hence, both Ccl2 and Il13 are sufficient to elicit MYC-HCC to metastasize, even if Twist1 is not expressed in the tumor cells." (PMID 31933479, 2020).
tumor (continued). "Increased TWIST1 expression was significantly associated with FIGO stage (P = .004), deep myometrial invasion (P = .007), LVSI (P = .02), and LNM (P = .001), but not correlated with differentiation (P = .14) and tumor size (P = .97)." (PMID 33235117, 2020). "Interestingly, tumor tissues from MKN45-SCD1 mice showed a significantly increased number of Twist1+ and Ki67+ cells, indicating SCD1 enhanced proliferation and metastasis as compared with tumor tissues from control ones (MKN45-Vector: 84.200 ± 2.478, MKN45-SCD1: 179.400 ± 2.926, P <0.0001)." (PMID 32726752, 2020). "Therefore, Twist1 drives metastasis of MYC-induced HCC without affecting primary tumor burden, MYC expression, tumor cell proliferation, apoptosis, invasiveness or EMT markers." (PMID 31933479, 2020). "In nonmetastatic BCC (nodular BCC), tumor cells were Twist1 negative." (PMID 31934531, 2019). "However, the molecular pathways through which TWIST1 and the downstream events are regulated during tumor metastasis have not been well characterized." (PMID 30154425, 2019). "In contrast to the original observation of proliferation regulation by its homodimer, SPZ1 activates and interacts with TWIST1 to form another functional bHLH dimer, which provides a plausible explanation for the mechanism by which SPZ1 transactivates TWIST1 expression during tumor progression." (PMID 30154425, 2019). "Immunohistochemical assay of tumor tissues revealed that PLC-PAR1 and HepG2/M/PAR1 overexpressing tumors exhibited high expression levels of VEGFR1, VEGFR2, VE-cadherin, and vimentin and a low expression level of E-cadherin while Twist1 silence reversed the regulation effects of PAR1." (PMID 30081924, 2018). "We studied a retrospective cohort of 160 consecutive surgically treated NSCLC patients with available frozen tumor samples for expression of EMT markers (CDH1, CTNNB1, CDH2, and VIMENTIN), inducers (TGFB1, c‐MET, and CAIX), and transcription factors (EMT‐TF:SNAI1, SNAI2, ZEB1, TWIST1, and TWIST2)." (PMID 29845746, 2018). "Recent studies reported that tumor cells may undergo MET, the reverse process of EMT, to colonize distant organs, which is induced by downregulation of the EMT-inducing transcription factors Twist1 and Prrx1." (PMID 29416649, 2018). "Specifically, proinflammatory cytokine IL-6 induces Twist1 expression in normal fibroblasts via STAT3 phosphorylation, and Twist1 then promotes the transdifferentiation of normal fibroblasts to CAFs via activation of a strong tumor-promoting chemokine, CXCL12, as well as suppression of senescence." (PMID 29029429, 2017). "Interestingly, of the EMT-TFs, Six1, the central mediator downstream of Twist1 and Snail1, significantly correlated with percent of PDX-bearing mice in which circulating tumour cells were found, suggesting a potential key role for this EMT-TF in metastatic dissemination." (PMID 28604738, 2017). "Histologic examination revealed that TE11 xenograft tumor exhibited more infiltrative tumor growth into surrounding tissue when they were co-injected with Twist1-expressing esophageal fibroblast (ENF8-Twist1) rather than control fibroblasts (ENF8-GFP) or tumor cell alone (TE11 only)." (PMID 29029429, 2017). "Importantly, continuous induction of TWIST1 in tumor cells that have reached distant organs did not result in increased macrometastases." (PMID 28085222, 2017). "According to our results, wogonoside could suppress tumor metastasis through inhibition of primary tumor invasion by increasing the expression of E-cadherin and decreasing the expression of MMP-9, vimentin and Twist1." (PMID 28774312, 2017). "Induction of tumor-derived endothelial differentiation by Twist1 was also different from the vasculogenic mimicry mechanism, because vasculogenic mimicry is the process by which aggressive tumor cells generate nonendothelial cell-lined channels delimited by extracellular matrix." (PMID 26823670, 2016).